PIK3CA (phosphatidylinositol-4,5-bisphosphate 3-kinase catalytic subunit alpha)
Diseases named in the same sentence as PIK3CA in open-access papers (continued):
Sharing a sentence is not in itself a finding about the gene and the disease.
breast cancer (continued). "Also, a study of genomic alterations in breast cancer patients revealed an association of phosphatidylinositol-4, 5-bisphosphate 3-kinase catalytic subunit alpha (PIK3CA) mutation with loco-regional recurrence in case of breast cancer." (PMID 31900196, 2020). "According to the circulating tumor DNA (ctDNA) sequencing results, about 50% of HR-positive metastatic breast cancers (MBCs) have PIK3CA missense mutations; 10-30% of metastatic triple-negative breast cancers (TNBC) and HER2-positive breast cancers have PIK3CA missense mutations." (PMID 31980592, 2020). "Moreover, PIK3CA mutations in human breast cancers, at E545K in exon 9 and H1047R in exon 20, have been reported even by studies using cell lines such as MCF10A immortalized breast epithelial cells." (PMID 33375317, 2020). "About 40% of HR-positive breast cancers harbor PIK3CA mutations." (PMID 32983983, 2020). "PIK3CA mutation frequency varies among breast cancer (BC) subtypes." (PMID 32637176, 2020). "Therefore, the objective of the present study was to evaluate the PIK3CA hotspot mutations in breast cancer patients in Saudi Arabia and in subsets of breast cancer cases based on hormone receptor expression." (PMID 31404155, 2019). "It is now believed that mutations of PIK3CA are found in 20–30% of all human breast cancers." (PMID 31905960, 2019). "In breast cancer patients, heterogeneity of the PIK3CA mutational status was widely discovered." (PMID 31650022, 2019). "PIK3CA gene mutation or amplification occurs in 26–36% of breast cancers." (PMID 31881983, 2019). "Mutations in the PIK3CA/AKT/mTOR pathway are frequent in breast cancer patients." (PMID 31088410, 2019). "In conclusion, the present study emphasized that PIK3CA mutations may serve as important biomarkers for breast cancer classification and for targeted therapies using PIK3CA inhibitors." (PMID 31404155, 2019). "Since approximately 35% of all breast cancers contain mutations in PIK3CA, these findings could have a significant impact." (PMID 30991934, 2019). "This was followed by PIK3CA which was mutated in 31% (1389/4485) of the breast cancer samples." (PMID 31881983, 2019). "The high purity levels obtained by MagSweeper make it suitable for downstream genomic analysis, such as genetic profiling of CTCs in breast cancer, single cell detection of phosphatidylinositol 3-kinase catalytic (PIK3CA) mutations in CTCs, and breast cancer metastases." (PMID 31088479, 2019). "However, we instead found that breast cancers with MAP3K1/PIK3CA co-mutations exhibit a strong luminal A phenotype." (PMID 31552290, 2019). "Notably, in primary breast cancer and metastatic breast cancer, the overall level of PIK3CA mutation is approximately 40.4%, while the overall level of PTEN loss is approximately 30.4%." (PMID 31514467, 2019). "Alterations in both, ERBB2 and PIK3CA, cover 14% of biomarkers associated to breast cancer." (PMID 31169290, 2019). "Furthermore, PIK3CA mutations are key drivers of breast cancer and its upregulation is associated with poor prognosis." (PMID 32010625, 2019). "Missense mutations in PIK3CA are commonly found in several types of breast cancers." (PMID 31905960, 2019).
breast cancer (continued). "PIK3CA mutations have also been correlated with response to therapy in breast cancer." (PMID 31905960, 2019). "Several studies have evaluated the correlation of PIK3CA mutations with clinicopathological parameters such as estrogen receptor (ER)/progesterone receptor (PR) positivity, the presence of lymph node metastases, and response to therapy in breast cancers." (PMID 31905960, 2019). "The possible reasons may include the different exonic mutations that may impact different mechanisms, the breast cancer-specific effect of PIK3CA mutations, and the impact of treatment, which greatly varies subsequent to recurrence." (PMID 31404155, 2019). "Overall, targeting S100A4 alone or in combination with driver mutations such as PIK3CA may provide a durable therapeutic intervention opportunity in aggressive breast cancers." (PMID 31881983, 2019). "For example, breast cancer cells with PIK3CA mutations may present as CSCs after MYC-induced reprogramming." (PMID 30283976, 2019). "Thus, co-occurrence of MAP3K1 and PIK3CA mutations is associated with a strong luminal A-like phenotype in ER+ breast cancer." (PMID 31552290, 2019). "In breast cancer, the concordance of PIK3CA mutation is 13.73% (28/204)." (PMID 31650022, 2019). "PIK3CA mutations are common in breast cancer with a reported rate of 25–40% of all breast cancers." (PMID 31693690, 2019). "PIK3CA is considered to be the most mutated oncogene in breast cancer." (PMID 32010625, 2019). "PIK3CA mutation is very common in breast cancer, where it appears to be an early, clonal event." (PMID 31374965, 2019). "PIK3CA mutations are found in ~ 30–40% of breast cancer patients." (PMID 31852484, 2019). "PIK3R1 has a lower frequency mutation than PIK3CA in breast cancer." (PMID 31777591, 2019). "PIK3CA gene was observed to be mutated in 175 breast cancer patients and 123 of them were confirmed to be functional (about 70.3%), which made PIK3CA to be the gene with the most confirmed mutations, even though it was not the most somatic mutated genes in breast cancer." (PMID 29485617, 2018). "Several trials were failed to found a significant association between PI3K inhibitors and PIK3CA-mutant breast cancer, which brings into question whether PIK3CA mutation are targetable in the clinic setting." (PMID 30235292, 2018). "However, there is currently insufficient evidence to recommend routine genotyping of PIK3CA in clinical practice, although many studies have been performed regarding the prognostic and therapeutic implications of PIK3CA mutations in breast cancer." (PMID 29707142, 2018). "Importantly, it is demonstrated that PIK3CA mutations are associated with lower pathological complete response (pCR) rates to HER2 targeted therapy in primary HER2-positive breast cancer." (PMID 29942710, 2018). "In this study, we analyzed the presence of PIK3CA mutations in formalin‐fixed, paraffin‐embedded, metastatic tissue and corresponding ctDNA from serum of patients with advanced breast cancer using a highly sensitive, optimized droplet digital PCR (ddPCR) assay." (PMID 29689598, 2018). "PIK3CA is the gene most frequently mutated in luminal breast cancer and whether these mutations cause resistance to endocrine therapy is a crucial issue." (PMID 30305115, 2018). "Also highly significant was apparent preferential selection for PIK3CA H1047R compared with multiple PIK3CA mutations, including PIK3CA E545K and E542K, in breast cancer, and for NRAS Q61K and Q61R above NRAS G12D and G13D in melanoma." (PMID 29748584, 2018).
breast cancer (continued). "A total of 160 PIK3CA somatic mutations, including 125 missense mutations, 8 silent mutations, 1 nonsense mutation, 19 deletion-frameshift mutations, and 7 insertion-frameshift mutations, have been reported in breast cancer in the TCGA7 and COSMIC8 databases." (PMID 29636477, 2018). "PIK3CA activating mutations are actionable for breast cancer (OncoKB evidence level 3)." (PMID 30442178, 2018). "We did not observe a correlation between the three prognostic groups and mutations of PIK3CA, which is the most frequently mutated oncogene in breast cancer (P = 0.96), as well as mRNA level of the MKI67 gene, which encodes for the proliferation-related Ki-67 antigen (P = 0.073)." (PMID 29996935, 2018). "Interestingly, although mutated genes are rarely common among the breast cancer samples, approximately 29%–45% of all luminal tumor samples harbor PIK3CA mutations." (PMID 28392480, 2017). "This hypothesis is further supported by recent evidence that mutated PIK3CA initiates breast cancer by triggering multiple key events during the cancer initiation stage 55." (PMID 27998038, 2017). "The predictive power of the FFL (PDGF/FLT1/SHC1) in the PIK3CA-mutated luminal-A tumor patients demonstrated in this study could be further validated in other breast cancer cohorts when genome sequencing data for these cohorts are available in the future." (PMID 28392480, 2017). "Therefore, to improve the predictive accuracy for therapeutic response, intrinsic subtypes of HER2-positive breast cancer should be stratified by molecular biomarkers, such as PIK3CA mutations, in future clinical studies." (PMID 28547525, 2017). "In addition, three patients in our cohort had the PIK3CA c.3140A>G (p.H1047R) mutation, which was recently reported as being crucial in inducing multipotency and heterogeneity of breast cancer." (PMID 28977883, 2017). "Although the clinical relevance of this combination remains to be clarified in colorectal cancer, in ER+/HER2- breast cancer, the PIK3CA activating mutation/low mTORC1 signaling was associated with better clinical outcomes to adjuvant ER-modulator (tamoxifen) treatment." (PMID 29137436, 2017). "Activating somatic mutations in PIK3CA are present in ~ 30% of human breast cancers of all stages." (PMID 28296140, 2017). "In contrast, most PIK3CA mutations occur early in the process of tumor development and its status does not change in the majority of patients who develop recurrent or progressive breast cancer." (PMID 28881720, 2017). "Interestingly, this also suggests a link to recent studies on genomic tumor evolution, reporting on an increase in activating PIK3CA mutation among cell free tumor DNA of breast cancer patients, following paclitaxel treatment." (PMID 28415744, 2017). "In addition, aspirin treatment of breast cancer cells carrying mutations in PIK3CA at either exon 9 (c.1633G>A) or exon 20 (c.3140A>G) also resulted in a significant decrease of cell viability." (PMID 29152088, 2017). "PIK3CA mutation is associated with ER + and PR + breast cancer." (PMID 28387221, 2017).
breast cancer (continued). "Mutations in EGFR, ERBB2, Erb-B2 receptor tyrosine kinase 3 (ERBB3) and Erb-B2 receptor tyrosine kinase 4 (ERBB4) (referred to hereinafter as ERBB family mutations) either occur alone or co-occur with PIK3CA mutations in 19% of HER2-positive breast cancers (n = 58)." (PMID 28750640, 2017). "To identify genes whose suppression converts the cytostatic response to PI3K inhibition into a cytotoxic response, we performed a positive-selection genome scale shRNA screen using MDA-MB-453 breast cancer cells, which harbor a PIK3CA H1047R mutation and ERBB2 amplification." (PMID 28561737, 2017). "Similarly, for oncogenes, we estimate that >10% of missense substitutions in PIK3CA in lung adenocarcinomas are passenger mutations, whereas only 1%–2% of such events in breast cancer are." (PMID 29056346, 2017). "In this study, we applied the Cancer Hallmark Network Framework to investigate how PIK3CA mutations interact with others in a luminal-breast cancer survival network and ask if the interactions could predict clinical outcomes." (PMID 28392480, 2017). "Thus, even though breast cancer cell lines harbor PIK3CA mutations or PTEN deficiency, such as HCC-1954 and HCC-1419, they are still sensitive to GDC-0941." (PMID 28881779, 2017). "Importantly, we found the luminal A breast cancer patients harboring the PIK3CA mutation and this positive regulatory loop in their tumors have significantly longer survival than those harboring PIK3CA mutation only in their tumors." (PMID 28392480, 2017). "Collectively, the significance of genotyping PIK3CA in clinical practice and targeted therapies based on the PIK3CA mutation in breast cancer remains unclear." (PMID 28387221, 2017). "PIK3CA mutations had been found at similar frequencies in breast ductal and lobular carcinoma, though we found there were a small difference based on TCGA breast cancer dataset." (PMID 29228676, 2017). "Earlier studies had found that activating PIK3CA mutations occur frequently in estrogen receptor (ER)-positive breast cancers, but treatment of such PIK3CA-mutant cancers with potent PI3K inhibitors induces an increase in ER-driven transcriptional programs that contribute to clinical resistance." (PMID 28532420, 2017). "Finally, the identified synergistic combinations were tested in two additional breast cancer cell lines harboring oncogenic PIK3CA mutations: BT-474 and MCF7." (PMID 27553366, 2016). "This is in line with a recent study that revealed that PIK3CA mutations may confer resistance in Her2-positive breast cancer." (PMID 26937901, 2016). "Thus, we conducted the first meta-analysis to evaluate the diagnostic performance of PIK3CA genotyping with cfDNA in breast cancer patients." (PMID 27336598, 2016). "BYL719 was initially evaluated in clinical trials for luminal breast cancer with PIK3CA mutations." (PMID 27048245, 2016). "Moreover, as PIK3CA mutational status in breast cancer was reported to change dramatically between primary tumors and corresponding metastatic, sequential biopsy is essential to monitor treatment response and disease progression." (PMID 27336598, 2016). "It is known that PIK3CA is the most frequently mutated gene in luminal/ER+ breast cancers." (PMID 27852980, 2016).
breast cancer (continued). "Since PIK3CA mutation was found in human breast cancer MCF-7 cells which might activate PI3K/Akt pathway, we recently investigated multifaceted activities of ZSTK474 on MCF-7 cells." (PMID 26918351, 2016). "Interestingly, the PIK3CA mutation rate in gastric cancer is less than that in colon and breast cancers." (PMID 27388016, 2016). "Therefore, we systematically reviewed studies on breast cancer to explore the diagnostic accuracy of detecting PIK3CA mutation in cfDNA." (PMID 27336598, 2016). "PIK3CA mutations are commonly associated with most breast cancer subtypes." (PMID 27941987, 2016). "We conclude that the spindle cell type of MBC with myoepithelial features exhibits a higher frequency of PIK3CA mutation than other types of metaplastic or basal-like breast cancer and may benefit from combined radio-/chemotherapy." (PMID 27220763, 2016). "Interestingly, in breast cancer AKT1(E17K) is mutually exclusive with PIK3CA and PTEN mutations, although in other cancers such as endometrial carcinoma, these mutations frequently co-exist in the same tumor." (PMID 27004402, 2016). "Some previous reports have suggested that patients with breast cancer who have PIK3CA mutations, have a better prognosis than others, whereas other authors have suggested that PIK3CA mutations are associated with a worse prognosis in colorectal cancer, endometrial cancer and lung cancer patients." (PMID 26701847, 2016). "Here, we demonstrate the importance of p110β in PIK3CA-mutated breast cancer cell lines." (PMID 27048245, 2016). "There was one partial response in a breast cancer patient with PIK3CA mutation." (PMID 26686201, 2016). "Comparable data were obtained for PIK3CA mutations in breast cancer patients." (PMID 27515171, 2016). "Finally, the good prognostic value of PIK3CA mutations has been emphasized in other cancer types, such as breast cancer, endometrial cancer, ovarian clear cell carcinoma, and esophageal squamous cell carcinoma 46–49." (PMID 25641861, 2015). "Mayer and Arteaga suggested, in an accompanying editorial, that the apparent discrepant role of PIK3CA mutations in early versus late ER+ breast cancer might be explained by a predominant role of PIK3CA mutations in secondary endocrine resistance." (PMID 25857348, 2015). "The drug had antitumor activity in breast cancer cell lines with PTEN or PIK3CA mutations." (PMID 26655726, 2015). "Most breast cancer recurrences retain their PIK3CA mutations, establishing it as a driver mutation." (PMID 25671134, 2015). "Notably, many studies examining the prognostic significance of PIK3CA mutations in breast cancer have been published, however very few included a large enough number of patients." (PMID 26452060, 2015). "However, in our patients, the mutation rate of PIK3CA in the ER positive breast cancer patients was found to be only 15.8% (24/152), which is significantly lower than that of 28–47% in the literature." (PMID 25816324, 2015). "PIK3CA mutations have been reported in 18-45% of breast cancer cases." (PMID 25671134, 2015).